MIB1 (MIB E3 ubiquitin protein ligase 1)
Diseases named in the same sentence as MIB1 in open-access papers (continued):
Sharing a sentence is not in itself a finding about the gene and the disease.
meningioma (continued). "Meningioma verification in the clinic depends primarily on HE histology and perhaps the immunohistochemical markers vimentin, epithelial membrane antigen (EMA), somatostatin receptor 2 (SSTR2), and Ki67/MIB-1." (PMID 37898750, 2023). "Established negative predictors of spinal meningioma recurrence are increased MIB-1 labeling indices, arachnoid invasion, and subtotal resection." (PMID 36091152, 2022). "As such, we first explored the usefulness of MIB-I LI in evaluating the proliferative potential of schwannoma cells because the predictive value of MIB-1 LI has not been as firmly established for VS as for meningiomas." (PMID 35323334, 2022). "Furthermore, we found a strong inverse correlation of both the primary and secondary MIB-1 labeling indices with the time to tumor recurrence in intracranial WHO grade 1 and 2 meningioma patients." (PMID 35453901, 2022). "In this study, the degree of resection and tumor immunoreactivity to MIB-1 (i.e., Ki-67 labeling index (LI)) are described in recurrent and non-recurrent meningioma cases." (PMID 29312841, 2017). "MIB-1 index is lower in MA area than that in meningioma area, indicating that MA is not the invasion component of meningioma." (PMID 23198201, 2012). "The MIB-1 antigen, cathepsin B and cathepsin L are shown to be expressed more on cells of recurrent meningiomas compared to non-recurrent ones." (PMID 22933900, 2010). "However, the meningioma recurrence score (MRS) generated by our machine learning algorithm revealed multiple predictive factors of recurrence, including age, female gender, and various histopathologic features, including the Ki-67/MIB-1 index." (PMID 40352015, 2025). "Finally, the small number of 12 cases of recurrence, may have caused bias in the results and thus to the excluded factors, such as MIB-1 LI, Simpson grade, WHO grade, which are recognized to affect the post-operative recurrence of meningiomas." (PMID 39790708, 2025). "Atypical or malignant meningiomas do not require higher MIB‐1 LIs for diagnosis." (PMID 37644780, 2023). "From 3 to 10% or more of MIB‐1 LIs of meningiomas have been reported to be related to higher recurrence rates or to be a prognostic factor for radiosurgical outcomes, whereas other studies have found that MIB‐1 LI is not useful for predicting tumor recurrence." (PMID 37644780, 2023). "Furthermore, the MIB-1 labeling index as well as the density of macrophage infiltrates significantly differs between skull base and non-skull base meningiomas." (PMID 38017560, 2023). "However, even in this subgroup, patients with a recurrent meningioma had a significantly higher MIB-1 labeling index compared to the patients without recurrence." (PMID 35453901, 2022). "MIB-1 antigen expression is higher in recurrent compared to non-recurrent meningiomas." (PMID 22933900, 2010). "Using histopathological criteria, atypical meningiomas were a distinct group and no specific criteria, except for MIB-1 labeling indices, could distinguish the low-proliferative atypical meningiomas from the high-proliferative atypical cases." (PMID 17937814, 2007). "However, there are also studies that could not identify a direct relationship between COX-2 and MIB-1 labeling index in meningiomas." (PMID 36077817, 2022). "Moreover, COX-2 expression has been correlated with a greater degree of invasiveness to the brain or the adjacent soft tissues, tumor recurrence, a higher MIB-1 labeling index and VEGF levels, suggesting it may play an important role in the development and growth of meningiomas." (PMID 25965831, 2015). "Three progressive meningioma cases had an increased MIB-1 labeling index (≥5%) and underwent a Simpson grade III resection, whereas the fourth patient with a meningioma progression had no increased MIB-1 labeling index (<5%) and underwent a Simpson grade IV resection." (PMID 35877258, 2022).
breast carcinoma (30 papers, 1995 to 2024). "A decrease in both Mib1 and Ki-67 expression levels is associated with a good response of breast cancer patients to preoperative treatment." (PMID 34503097, 2021). "Cyclin E, a regulator of the cell cycle, and Ki-67/MIB1, a diagnostic biomarker in proliferating cancer or malignant tumor cells, affect the behavior of human breast cancer cells and uLMS." (PMID 34563053, 2021). "Mib1 (antibody against Ki-67) proliferation index remains a reliable diagnostic biomarker of breast cancer, similarly to Ki-67." (PMID 34503097, 2021). "Our results revealed that loss of nesprin-2 in breast cancer tissue was associated with the MIB1 index (P < 0.05), which correlates with cell growth." (PMID 26175118, 2015). "In the series of 75 luminal breast cancers, a mean of 18% [7 to 38%] cells were stained by MIB-1 antibodies using KI67 and 46/75 (64%) samples were considered as proliferative tumors, by automated counting." (PMID 29662649, 2018). "Given that tumors with high proliferative index occurs in patients with poor clinical outcome, MIB-1 is a potentially reliable prognostic marker in this hormonally resistant subtype of breast cancers." (PMID 24586570, 2014). "Mib1 scores of >20 and ≤20 classify breast cancer into respectively faster and slower proliferating diseases with corresponding poorer or better survivals." (PMID 23658799, 2013). "MIB-1-based proliferative fraction of breast carcinomas thus can be taken into consideration when defining an adjuvant treatment plan for cancer patients." (PMID 22662150, 2012). "In one report, E2F-1 protein correlated with Mib1/Ki67 expression and was expressed at higher levels in advanced-stage breast cancer." (PMID 19891787, 2009). "MIB-1 immunostaining can be used as an effective method of assessing proliferation in human breast carcinomas." (PMID 8605100, 1996). "The MIB1 labelling index was studied using a CAS 200 image analyser in 177 tumours from women with primary operable breast carcinoma in whom long-term follow-up data were known." (PMID 7819031, 1995). "Although the membrane‐positive expression of MIB‐1 has also been reported in breast cancer, salivary gland pleomorphic adenoma, sclerosing haemangioma of the lung, renal oncocytoma, and sarcomatoid pleural mesothelioma, these patterns were not clinically significant or reproducible." (PMID 39447085, 2024). "Some of these proteins have been reported to be breast cancer related markers, such as Ki-67 (MIB-1) and CA15-3 being blood secretory protein markers for breast cancer, and C-telopeptide of collagen type I, which contains two chains, being urine excretory protein markers." (PMID 26375396, 2015). "The Mib1 score provides a particularly strong prognostic marker in human breast cancer." (PMID 23658799, 2013). "The correlation between a high MIB-1 index and poor prognosis is well known in breast cancer." (PMID 23426606, 2013). "Fifty consecutive breast cancer cases with both a core biopsy and a surgical sample available, without intervening neo-adjuvant therapy, were collected and tumor proliferation (Ki67, MIB1 antibody) was assessed immunohistochemically." (PMID 21819622, 2011). "We have investigated the use of the antibody MIB1 as a proliferative and prognostic marker in breast cancer and whether changes in proliferative activity could account for differences in prognosis of premenopausal women operated on during different phases of the menstrual cycle." (PMID 9652769, 1998). "Several genes found on chromosome 18, such as SMAD4, SMAD2, MIB1, and MBD1, are involved in breast cancer development and progression." (PMID 38803515, 2024). "For instance, MIB1 has been shown to ubiquitinate JAG1 and activate Notch signaling in breast cancer." (PMID 33793053, 2021).
breast carcinoma (continued). "According to 13th St Gallen International Breast Cancer Conference classification, seventeen patients relapsed as luminal B-like disease (HR+, HER2-, Mib1 ≥ 20%), and eight were luminal A-like BCs (HR+, Mib1 <20%)." (PMID 30140695, 2018). "In breast cancer tissue, 13-HODE stood alone in being significantly related to this classification: it was >3.3-fold higher in patients with >20 Mib1 scores." (PMID 23658799, 2013). "A 5-gene assay was also developed quantifying the expression of CHDH, HOXB13, IL17BR, MIB1 and MKI67 to identify a subgroup of early stage estrogen receptor–positive breast cancer patients with very poor outcome despite endocrine therapy." (PMID 23468873, 2013). "Higher risk of relapse in both node positive and negative as well as worse survival outcome in early breast cancer has been observed in tumors with MIB-1 positive." (PMID 24586570, 2014).
glioma (22 papers, 2011 to 2025). A benign or malignant brain and spinal cord tumor that arises from glial cells (astrocytes, oligodendrocytes, ependymal cells). "Although a correlation to histological grade in pediatric glioma has repeatedly been reported, several studies furthermore conformably show an association of KI-67/MIB-1 LI and PFS in pediatric high-grade glioma." (PMID 38580878, 2024). "The Ki-67/MIB-1 labeling index (LI) is one of the immunohistochemical markers used for discriminating between high and low-grade gliomas, whilst its use as prognostic factor for the stratification is still discussed." (PMID 37227648, 2023). "The Ki-67/MIB-1 labeling index (LI) is clinically used to differentiate between high and low-grade gliomas, while its prognostic value remains questionable." (PMID 37227648, 2023). "MDWI-derived DDC1500 and DDC5000 negatively correlated with MIB-1 expression in all glioma patients (P<0.05)." (PMID 37182187, 2023). "Some well-known ancillary markers of grading gliomas, such as anti-MIB-1/Ki-67 and anti-CD34, are closely related to tumor cell proliferation and microvascular density." (PMID 37182187, 2023). "The proliferation marker Ki-67 (or MIB-1) has been suggested as an ancillary marker in the grading of gliomas." (PMID 29885671, 2018). "A high level of interobserver variability for the Ki-67/ MIB1 LI between pathologists has previously been demonstrated in gliomas." (PMID 29885671, 2018). "Remarkably, glioma grade can be successfully predicted by the significant association of rCBV, Cho/Cr ratio and 18F-FDG SUVmax with the histological P-1 and the Ki-67/MIB-1 LI." (PMID 29207673, 2017). "The T/N ratio of 18F-FDG PET was also positively correlated with the MIB-1 LI in all gliomas (rs = 0.400, p = 0.013), whereas the SUVmax of 18F-FDG PET was not correlated (rs = 0.242, p = 0.144)." (PMID 28567708, 2017). "Previous studies have shown that MIB-1 LI is correlated with poorer survival in gliomas across all histological grades." (PMID 24265731, 2013). "Additionally, IGF2BP3 knockdown-induced NETosis suppression and glioma cell survival was rescued by MIB1 overexpression." (PMID 38167409, 2024). "While KRT24, itself, has not been studied in the context of glioma, it has been experimentally determined to be associated with MIB1 and MIB2, which are involved in Notch signaling pathway in brain tumors." (PMID 31475119, 2019). "Several clinical values of MIB-1 LI have been reported in human gliomas." (PMID 22734595, 2012). "The purpose of this study wasto analyze the recurrence patterns and to evaluate whether MIB-1 LI could be useful as amarker to predict the pattern of failure in high-grade glioma." (PMID 22734595, 2012). "The purpose of the present study was to analyze the recurrence pattern ofhigh-grade glioma treated with a multimodal treatment approach and to evaluatewhether the MIB-1 labeling index (LI) could be a useful marker for predicting thepattern of failure in glioblastoma (GB)." (PMID 22734595, 2012). "We further revealed that the IGF2BP3/MIB1/FTO pathway forms a positive feedback loop in both T98G cells and primary cultured human glioma cells." (PMID 38167409, 2024). "However, the function of circRNAs derived from MIB1 in glioma remains unknown." (PMID 39698112, 2024). "Overexpression of FTO effectively suppressed the IGF2BP3-induced upregulation of MIB1 and overall increase in m6A, inhibiting IGF2BP3-induced NETosis and glioma cell survival." (PMID 38167409, 2024). "In this work, we report that IGF2BP3 initiates a reciprocal regulation between MIB1 and FTO to drive m6A-mediated NET formation and glioma progression." (PMID 38167409, 2024). "In this study, we demonstrate that, in glioma, upregulation of IGF2BP3 enhances the expression of E3 ubiquitin protein ligase MIB1, promoting FTO degradation via the ubiquitin-proteasome pathway." (PMID 38167409, 2024).
glioma (continued). "MIB1 also plays a role in angiogenesis and MIB2 may be a positive regulator of NF-kB signaling, both of which are important in glioma pathogenesis." (PMID 31475119, 2019). "T/N ratio of 18F-FAMT PET was not correlated with MIB-1 labeling index in all gliomas, whereas T/N ratio of 18F-FDG PET was positively correlated (rs = 0.400, p = 0.013)." (PMID 28567708, 2017). "Neither the SUVmax nor the T/N ratio of 18F-FAMT PET was correlated with the MIB-1 LI in all gliomas (SUVmax: rs = 0.138, p = 0.408; T/N ratio: rs = 0.290, p = 0.077)." (PMID 28567708, 2017). "In addition, MIB-1 LI can beconsidered as an important proliferation parameter, and may be associated with clinicalgrowth parameters independent of other prognostic factors in gliomas." (PMID 22734595, 2012). "The T/N ratios of 18F-FAMT were not correlated with MIB-1 LI in all gliomas." (PMID 28567708, 2017). "In our cohort, the ratio of diffuse astrocytoma was small, and the larger ratio of oligodendroglial tumor may have affected our results suggesting the T/N ratio of 18F-FAMT PET was not correlated with MIB-1 LI in all gliomas." (PMID 28567708, 2017).
glioblastoma (11 papers, 2008 to 2023). The most malignant astrocytic tumor (WHO grade IV). "In one of the glioblastoma cases of our initial cohort, we noted that HAVOC partitioning captured a BRAFV600E-mutated tumor subclone, showing an elevated Ki-67 (MIB1) proliferation index on immunohistochemistry." (PMID 37774029, 2023). "The anterior temporal lesion showed mild hypercellularity and cellular atypia with only a few MIB1 positive cells, consistent with recurrent glioblastoma." (PMID 29490632, 2018). "The left temporal resection done 2 weeks later demonstrating hypercellularity, increased mitosis, vascular proliferation, pseudopalisading necrosis consistent with active glioblastoma with the highest MIB1 of 15%." (PMID 29490632, 2018). "Immunohistochemical expression of MIB-1 and DJ-1 was evaluated in 111 samples of astrocytic tumors comprising 28 diffuse astrocytomas, 38 anaplastic astrocytomas and 45 glioblastomas." (PMID 23902708, 2013). "In the present study, we have investigated the power of Ki-67/MIB-1 expression as prognosticator in a large and homogenous group of patients suffering from IDH wild-type Glioblastoma (IDHwt GBM) prognostic impact of the Ki-67/MIB-1 labeling index." (PMID 37227648, 2023). "Histologically the tumor was a WHO grade IV glioblastoma with wild-type IDH (IDHwt) by immunohistochemistry, with a high mitotic index (MIB1 > 50%), prominent microvascular proliferation, and geographic necrosis." (PMID 34355174, 2021). "Immunohistochemistry staining showed glioblastoma multiforme (GBM) with E3 ubiquitin-protein ligase MIB (MIB)-1 (Ki-67) proliferation index of 23 to 25%, trioctyl phosphine oxide (TOPO) (++), and phosphatase and tensin homolog deleted on chromosome ten (PTEN) (++)." (PMID 26091464, 2015).
lung carcinoma (6 papers, 2022 to 2024). "For example, in lung cancer, MIB1 is involved in epithelial–mesenchymal transition, cell migration and cell survival, MIB1 aslo can be used as a marker for the proliferation and prognosis of LGG in children." (PMID 39698112, 2024). "It has been found that the proliferation of lung cancer tissue, as determined by Mib-1, is inversely related to the expression of GRX1 and GRX2." (PMID 38256132, 2024). "When Nrf2 is degraded by E3 ubiquitin ligase (MIB1), the antioxidant capacity of lung cancer cells is weakened, and the sensitivity of lung cancer cells to ferroptosis inducers is enhanced." (PMID 37005430, 2023). "Research showed that in lung cancer, the proteasomal degradation of NRF2 protein promoted by the E3 ligase MIB1 could sensitize lung cancer cells to ferroptosis and that the suppression of NRF2 expression and activity could be a novel approach to controlling LUAD clinically." (PMID 36358651, 2022). "For example, the E3 ligase MIB1 promotes proteasomal degradation of NRF2 and sensitizes lung cancer cells to ferroptosis." (PMID 36175889, 2022). "The mRNA level of NEDD4L but not MIB1, WWP1, or other ligases was downregulated in patients with lung cancer." (PMID 37240137, 2023).
melanoma (6 papers, 2018 to 2025). A malignant, usually aggressive tumor composed of atypical, neoplastic melanocytes. "There is good correlation between MIB-1 reactivity in primary thick melanomas and metastatic potential and there is a association between loss of HLA class I and II antigens with a more aggressive nature of the tumor." (PMID 41561965, 2025). "The differentiation to intermediate–grade (Ki67/MIB1–proliferation index of 5–10%) MM and malignant transformation into melanoma (Ki67/MIB1–proliferation index of >10%) is particularly important." (PMID 36497333, 2022). "As double staining of MIB-1 (anti-Ki-67) and HMB45 (anti-gp100) was unsuccessful, we replaced gp100 with the melanoma-associated marker Melan A14." (PMID 29426936, 2018). "Almost all melanoma cells in the chick embryo were MIB1-positive, clearly demonstrating the proliferative activity and viability of the transplanted cells." (PMID 29454361, 2018). "To confirm the viability of the melanoma cells, we performed anti-Ki67 (MIB1) immunohistochemistry." (PMID 29454361, 2018). "In contrast, malignant melanomas display larger, atypical, spindled pigmented cells with higher mitotic activity (average 5.7 per 10 high-power fields), they frequently have irregular eosinophilic nuclei with numerous mitotic figures, and an elevated MIB-1 labeling index (mean, 8.1%)." (PMID 41303082, 2025). "The melanoma markers MLANA (MART-1), TYR, HMB45 (PMEL), SOX10, S100, and the proliferation marker MIB-1, which recognizes the Ki67 antigen, are used to diagnose primary and metastatic melanoma." (PMID 37762707, 2023).